TGFB1 (transforming growth factor beta 1)
Diseases named in the same sentence as TGFB1 in open-access papers (continued):
Sharing a sentence is not in itself a finding about the gene and the disease.
adenomyosis (31 papers, 2016 to 2025). The growth of endometrial tissue inside the muscular wall of the uterine corpus. "We provide evidence that endometrial TGFβ1 may cause fibrosis in endometrium and ectopic endometrium may participate in uterine adenomyosis." (PMID 30695033, 2019). "In external adenomyosis, the analysis predicted the activation of multiple upstream regulators such as LPS, TGFB1, IL4, and IFNG." (PMID 40531845, 2025). "Next, IHC was performed to examine the (myo)fibroblast, CTGF, TGFβ1, and collagen expression patterns in the endometrium specimens with adenomyosis." (PMID 30695033, 2019). "Although the expression of TGFβR and CTGF was found to be indifferent at EMJZ in adenomyosis uteri, higher expression of TGFβR ligand such as TGFβ1 may act as an important player in inducing adenomyosis." (PMID 30695033, 2019). "In conclusion, we demonstrate here that TGFβ1, CTGF, and collagen are expressed in subepithelial stroma region of the endometrium with adenomyosis, in which it is abundant of fibroblasts with positive vimentin staining." (PMID 30695033, 2019). "It has been shown that TGFβ1 drives EMT and FMT in adenomyosis development both in animal model and in human, although the expression of TGFβ receptor type I to III and CTGF was found to be indifferent at EMJZ in adenomyosis uteri." (PMID 30695033, 2019).
chronic asthma (31 papers, 2008 to 2025). An asthma that is characterized by the development of persistent airway inflammation and recurrent attacks of breathlessness and wheezing, which vary in severity and frequency. "TGFβ1 was substantially higher in mice with acute asthma than those with chronic asthma in the present study." (PMID 34671356, 2021). "TGFβ1/Smad3 is crucial in promoting airway remodeling in chronic asthma, and this phenomenon was also verified in this study." (PMID 34671356, 2021). "Accordingly, changes in the expression of TGFβ1/Smad3 and collagen I in the airways with acute and chronic asthma were detected via immunofluorescence." (PMID 34671356, 2021). "Since TGFβ1 is a well known mediator of airway remodeling in chronic asthma, we next investigated the effect of AR inhibition on TGFβ1-induced changes in the expression of structural proteins in SAECs and mLFs." (PMID 23460857, 2013). "The evidence of increased expression of Igf1 is consistent with our earlier published evidence in a related animal model of chronic asthma, in which upregulation of Igf1, Fgf1 and Tgfb1 mRNA was demonstrated in the airway epithelium." (PMID 23611895, 2013). "Since neutrophils infiltrate airways in severe and chronic asthma, their ability to mediate production of TGFβ1 may affect airway remodeling seen in this group of patients." (PMID 24982697, 2014). "In chronic asthma patients, TGFβ1–induced p38 MAPkinase mediates airway epithelial cells apoptosis resulting in their detachment causing an injury, which along with impaired repair processes, leads to inflammatory and remodeling responses in the underlying submucosa." (PMID 23460857, 2013). "Moreover, in the mouse model of chronic asthma, SAM showed anti-inflammatory and anti-fibrotic effects, by inhibition of TGFβ1 signaling and reduction of oxidative stress." (PMID 34845494, 2022). "However, TGFβ1 and p-Smad3 expression slightly decreased in the OVA-induced chronic asthma compared with the acute asthma group." (PMID 34671356, 2021). "Overall, the present study was the first to demonstrate that the high expression of SDC-1 in the trachea of patients with chronic asthma is closely related to airway remodeling, and SDC-1 may regulate collagen deposition in epithelial cells or fibroblasts through the TGFβ1/Smad signaling pathway." (PMID 34671356, 2021).
disc degeneration (31 papers, 2006 to 2025). "The predictive analysis identifies the TGFβ-1 gene as the most promising candidate associated with Intervertebral Disc Degeneration (IDD), with isoforms TGFβ-2 and TGFβ-3 also receiving prioritization." (PMID 38745993, 2024). "Notably, TGFβ-1 emerges as the highest-scoring gene in DisGeNET’s curated dataset related to disc degeneration." (PMID 38745993, 2024). "In conclusion, we demonstrate the potential of TGFβ1 and CTGF to mitigate the progression of disc degeneration and the potential use of these molecules in a molecular therapy to treat the degenerative disc." (PMID 28358123, 2017). "We further demonstrated the potential utility of a combination of TGFβ1 and CTGF as novel, minimally invasive molecular therapeutic agents for the biological treatment of degenerative disc disease." (PMID 28358123, 2017).
cyst (30 papers, 2011 to 2026). A sac-like closed membranous structure that may be empty or contain fluid or amorphous material. "Key words:Periapical cyst, radicular cyst, residual cyst, transforming growth factor beta 1 (TGF-β1), intercellular adhesion molecule 1 (ICAM-1), ki-67." (PMID 27918735, 2017).
eosinophilia (29 papers, 2006 to 2026). "In accordance with this animal model, treatment of mild atopic asthmatics for 2 months with anti-IL-5 Ab (mepolizumab) was shown to be successful in reducing tissue eosinophilia, lung TGFβ1 expression and deposition of ECM components in the lamina reticularis." (PMID 17892594, 2007). "Indeed, the response dynamics unique to BN rats reflect a scenario of on-going eosinophilia and exacerbated airways inflammation driven by growth factors, TGFβ1 in particular." (PMID 34367159, 2021). "This remodeling was accompanied by increased expression of TGFβ1 in the bronchial epithelium without airway eosinophilia suggesting heterogeneous upstream mechanisms mediate airway remodeling." (PMID 24982697, 2014). "We show that our model of chronic respiratory HDM challenge resulted in the expected robust induction of murine peribronchial inflammation, airway mucus production and eosinophilia, increased serum IgE and lung expression of mucins, Tgfb1, and Il13ra2, regardless of surgery status." (PMID 36926031, 2023).
gastric tumors (29 papers, 2007 to 2025). "TGFβ1 may be associated with gastric tumour progression by indirectly stimulating angiogenesis through the upregulation of VEGF expression." (PMID 24137336, 2013). "TGFB1-mutated mice exhibited decreased levels of active TGFB1, reduced TGFB signaling, and stomach tumors, suggesting that the association of LTBPs with the latent TGFB complex is important for proper TGFB1 function in GC." (PMID 40075643, 2025). "Transforming growth factor beta 1 (TGF-β1) induces Foxp3+ regulatory T cells (Tregs), and TGF-β1 from gastric tumors inhibits anti-tumor immunity in the tumor microenvironment via this mechanism." (PMID 36814928, 2023). "In the gastric tumors, many of these genes are regulated by ETS2, BMP4, and TGFB1 and by the kinases MAPK1(ERK) and CCNK and the transcription regulators E2F, CBX5, and CCND1." (PMID 31584998, 2019). "We previously demonstrated the clinicopathological significance of several cancer-associated molecules including fibroblast growth factor receptor 2 (FGFR2), transforming growth factor-beta 1 (TGFβ1), C-X-C chemokine receptor 2 (CXCR2), CXCR4, and phospho-Smad2 expressed at primary gastric tumors." (PMID 35650563, 2022).
proliferative vitreoretinopathy (29 papers, 2010 to 2026). Vitreoretinal membrane shrinkage or contraction secondary to the proliferation of primarily retinal pigment epithelial cells and glial cells, particularly fibrous astrocytes, followed by membrane formation. "In addition, TGFβ1 is believed to have an important role in the pathogenesis of fibrotic diseases in the eye including proliferative vitreoretinopathy." (PMID 24710116, 2014).
tendinopathy (29 papers, 2012 to 2025). "In this study, the association of TGFB1 gene polymorphisms with the effectiveness of lateral elbow tendinopathy (LET) treatment with PRP was investigated." (PMID 40141076, 2025). "Transforming growth factor beta 1 gene (TGFB1) seems to be a suitable candidate for analysis of PRP effectiveness in tendinopathy due to its association with wound healing, tendon development, and pain sensation and its presence in PRP." (PMID 40141076, 2025). "This TGFβ1-injection model of tendinopathy also explored the role of glucose metabolism in tendon injury in both wild type and Adamts5−/− (TS5KO) knockout mice." (PMID 32095779, 2019). "Studies on a TGFβ1-induced murine tendinopathy model showed that initiation and progression of the pathology was accompanied by marked changes in the expression of chromatin-modification enzymes." (PMID 27902739, 2016). "TGFβ1 injections activated the Warburg pathway, which generates lactate from glucose under normoxia rather than just hypoxia, inhibits mitochondrial energy production, and contributes to tendinopathy." (PMID 32095779, 2019). "Running upregulated expression of Col III and insulin-like growth factor (IGF)-I, but downregulated TGFβ1, connective tissue growth factor (CTGF), and ECM components fibromodulin and biglycan, with no impact on Col I. Notably, these gene expression profiles are not observed in human tendinopathies." (PMID 32095779, 2019).
atopic dermatitis (28 papers, 2007 to 2025). "TGFβ1 may have a therapeutic potential for atopic dermatitis as it is an important fibrogenic and immunomodulatory factor that regulates cellular processes implicated in the suppression of atopic dermatitis skin lesions." (PMID 38262937, 2024). "Moreover, there is evidence that IL-10 and transforming growth factor beta 1 (TGFβ1) are important mediators in inducing tolerance and preventing atopy, and it was shown that polymorphisms of the TGFB1 gene associated with low production of this cytokine predisposes individuals to atopic dermatitis." (PMID 34884743, 2021). "In fact, some reports suggest an association between low TGFβ1 responder genotype and low TGFβ1 mRNA production by circulating leukocytes in some children with atopic dermatitis." (PMID 18053185, 2007). "However, one study examining the TGFB1 gene in patients with atopic dermatitis found that the mean age of these patients was 8 years, with the youngest being 1 year old." (PMID 39859044, 2025).
cystic fibrosis (28 papers, 2010 to 2026). Autosomal recessive disorder caused by pathogenic variants in the CFTR gene (cystic fibrosis transmembrane conductance regulator), which encodes a chloride and bicarbonate channel expressed in epithelial cells, and follow the diagnosis criteria. "One well-known example of such modifier genes is TGFB1 in cystic fibrosis with specific variants associated with greater disease severity." (PMID 33666875, 2021). "Two polymorphisms in TGFβ1, −509, and +869, which elevate plasma levels of TGFβ1, increase the severity of cystic fibrosis and familial pulmonary hypertension." (PMID 26540410, 2015). "We also show TG2’s ability to regulate TGFβ1 signalling in both endothelial cells and in cardiac fibroblasts, an observation which we recently demonstrated in cystic fibrosis bronchial epithelial cells." (PMID 29795262, 2018). "We were able to show that TGFβ1 in serum correlates negatively with lung function in cystic fibrosis." (PMID 24062613, 2013). "So far, few studies have measured TGFβ1 levels in cystic fibrosis patients." (PMID 24062613, 2013).
Hydrocephalus (28 papers, 2006 to 2025). Hydrocephalus is an active distension of the ventricular system of the brain resulting from inadequate passage of CSF from its point of production within the cerebral ventricles to its point of absorption into the systemic circulation. "This inflammatory milieu generates free radicals and pro-inflammatory cytokines such as interleukin (IL)-6, IL-4, tumor necrosis factor-α (TNFα), and transforming growth factor-β1 (TGFβ1), which contribute to the development and progression of hydrocephalus." (PMID 37794877, 2023). "In the Tgfb1 overexpression model, the changes of matrix metalloproteinase-9 (Mmp-9) and its inhibitor Timp-1 were found to be important factors for developing hydrocephalus due to ECM environment alterations." (PMID 35047005, 2021). "It has been shown in a transgenic mouse model, in which astrocytes over-express TGFβ-1, that hydrocephalus ensues." (PMID 16737542, 2006). "However, in animal models of obstructive hydrocephalus, including the hyh mouse, TGFβ1 expression is decreased or unchanged." (PMID 36982724, 2023). "In cerebral ischemia, TGFβ-1 appears to be neuroprotective but it may have an adverse effect in IVH-induced and other forms of hydrocephalus." (PMID 28351417, 2017).
interstitial lung disease (28 papers, 2010 to 2026). A diverse group of lung diseases that affect the lung parenchyma. "TGFB1 signaling has a central role in interstitial lung disease and inhibition of TGFB1 by a non-toxic small molecule mitigates damage in a cell model." (PMID 38980870, 2024).
infertile (27 papers, 2010 to 2025). "Genetic deficiency of TGFB1 can cause male infertility and the infertility phenotype can’t be rescued by exogenous supplementation." (PMID 31855573, 2019). "A reliable decrease in endometrial TGFβ1 and bFGF2 concentrations in combination with increased DEFa1 concentration was demonstrated in the infertile group relative to the fertile group." (PMID 37108732, 2023). "An analysis in infertile women showed that the expression level of transforming growth factor-beta 1 (TGF-β1) in blocked fallopian tubes was independently and inversely correlated with the postoperative pregnancy outcomes." (PMID 33092547, 2020). "Recently, we showed that transforming growth factor beta 1 (TGFβ1)-induced MSCs improved SSCT efficiency in an infertile mouse model." (PMID 31640769, 2019). "It has been reported that the levels of IL-2, IL-6, IL-10 and TGFB1 in seminal plasma or serum are significantly elevated in infertility patients compared to healthy controls." (PMID 31855573, 2019). "A mouse model for long-term infertility was used to transplant SSCs (SSCT, n = 10) and a combination of SSCs and TGFβ1-treated MSCs (MSi-SSCT, n = 10)." (PMID 31640769, 2019).
papillary thyroid cancer (27 papers, 2013 to 2025). "Moreover, curcumin was demonstrated to inhibit metastasis in human papillary thyroid carcinoma cells by downregulating components of the prometastatic signaling pathway TGFB1/SMAD2/SMAD3." (PMID 34422220, 2021). "In thyroid tissues, strict regulation of transcriptional activity of TGFβ1 and their receptors TGFβRI-III genes observed in normal tissues is completely disturbed in papillary thyroid cancer (PTC)." (PMID 38085441, 2024). "We genotyped TGFB1, TGFBR1, and TGFBR2 SNPs in 157 papillary thyroid cancer (PTC) patients and 200 healthy controls." (PMID 33905626, 2021).
astrocytomas (26 papers, 2000 to 2025). "To determine the spatial relationship between TGFB1 signaling and GAM density in high-grade astrocytoma, we performed immunofluorescence targeting Iba-1 and TGFB1." (PMID 34131649, 2021). "Together, these data indicate that TGFB1 directly contributes to the malignant phenotype of canine astrocytoma cells." (PMID 34131649, 2021). "Our data also support a contributing role for TGFB1 signaling in the malignant phenotype of canine astrocytoma." (PMID 34131649, 2021). "A profile with a relatively small number of proteins (ANGPT1, TIMP1, IP10, TGFβ1) was sufficient to correctly assign 79.7% (47/59) of the astrocytoma and 65.1% (28/43) of the control subjects." (PMID 31861636, 2019). "Therefore, we assessed in vitro features of malignancy of 2 canine astrocytoma stem cell lines (0514, 1110) following exposure to TGFB1." (PMID 34131649, 2021). "We identified that relative TGFβ1 protein levels in astrocytoma patient serum samples before surgery may help in evaluating protein profiles." (PMID 31861636, 2019). "In conclusion, the serum protein profiles of ANGPT1, TIMP1, IP10, and TGFβ1 were associated with the presence of astrocytoma independent of its malignancy grade, while OPN and IP10 were associated with GBM patient survival." (PMID 31861636, 2019). "Moreover, TGFB1 enhanced the migration of canine astrocytoma cells in vitro." (PMID 34131649, 2021). "However, TGFB1 IR was heterogeneously distributed throughout high-grade astrocytomas." (PMID 34131649, 2021). "In GBM and Astrocytoma °II/°III specimens, as well as in primary GBM cells, we found significantly increased expression levels of DVL2 and TGFB1." (PMID 30366472, 2018). "Notably, GBM exhibited higher levels of TGFB1 and DVL2 as compared to Astrocytoma °II/°III (TGFB1: induction 1.5-fold ± 0.36, p = n.s.; DVL2: induction 2.1-fold ± 0.3, p < 0.001; n = 10 for Astrocytoma °II/°III)." (PMID 30366472, 2018).
cataract (26 papers, 2007 to 2025). Partial or complete opacity of the crystalline lens of one or both eyes that decreases visual acuity and eventually results in blindness. "In earlier studies, we found that LECs from Shumiya Cataract Rat (SCR) lenses with cataract displayed reduced expression of Prdx6, and higher expression of TGFβ1 and α-SMA." (PMID 23205574, 2013). "In PBMCs, the expression of TGFβ1 and TGFβ2 was about twofold higher in the congenital cataract patients compared to the patients with traumatic cataracts, and a statistical significance was found (TGFβ1 p<0.0001, TGFβ2 p<0.0001, Mann–Whitney U test)." (PMID 22128246, 2011). "Significant differences were found for TGFβ1 and TGFβ2 expression profiles in PBMCs between the patients with congenital and traumatic cataracts." (PMID 22128246, 2011). "Our results revealed that TGFβ1 was a predominant isoform in ALCs, whereas TGFβ3 was a major isoform in PBMCs in patients with congenital and traumatic cataracts." (PMID 22128246, 2011). "In the present study, real-time quantitative reverse transcription (QRT)-PCR was applied to investigate the changes in TGFβ1, TGFβ2, and TGFβ3 gene expression in fragments of ALCs and PBMCs from pediatric patients with congenital and traumatic cataracts." (PMID 22128246, 2011). "In ALCs, there was no significantly different expressions of TGFβ1, TGFβ2, and TGFβ3 between congenital and traumatic cataracts (TGFβ1 p=0.78, TGFβ2 p=0.75, TGFβ3 p=0.23, Mann–Whitney U test)." (PMID 22128246, 2011). "Overexpression of TGFβ1 and TGFβ2 in the PBMCs of patients with congenital cataracts might indicate the involvement of these cytokines in the development of lens opacity." (PMID 22128246, 2011). "Likewise, our results revealed higher mRNA levels of TGFβ1 and TGFβ2 in ALCs of traumatic cataract patients." (PMID 22128246, 2011). "For traumatic cataracts, a positive correlation was only observed between the expression of TGFβ1 and TGFβ2 in ALCs, whereas for PBMCs, a positive correlation was only affirmed between the expression of TGFβ1 and TGFβ3." (PMID 22128246, 2011). "Overexpression of TGFβ1 and TGFβ2 in the PBMCs of patients with congenital cataracts might indicate that these cytokines are involved in the development of lens opacity." (PMID 22128246, 2011). "Interestingly, the subjects with congenital cataracts showed a significant elevation of TGFβ1 and TGFβ2 expression in PBMCs when compared to those with traumatic cataracts, which suggests that traumatic cataractogenesis is mediated differently from congenital cataractogenesis." (PMID 22128246, 2011). "Compared with the cataract group, the concentration of IL-8, MMP-2, MMP-3, MMP-9, TGFβ-1, TGFβ-3, and TNF-α was significantly increased in subjects with JIAUwG or JIAUwoG." (PMID 29675026, 2018). "TGFβ1, TGFβ2, and TGFβ3 isoforms were detected in ALC and PBMC samples obtained from patients with congenital and traumatic cataracts." (PMID 22128246, 2011).